CCL22 (C-C motif chemokine ligand 22)
Diseases named in the same sentence as CCL22 in open-access papers (continued):
Sharing a sentence is not in itself a finding about the gene and the disease.
tumor (continued). "The level of CCL22 in the MPE is significantly higher than that of serum, and classical pleural CCL22 has been found to be mainly produced by macrophages, T cells, and malignant tumour cells." (PMID 38475858, 2024). "High-throughput single-cell RNA sequencing (scRNAseq) revealed that PAZ@Fe-MOF significantly reduced pro-tumorigenic M2-like macrophage populations at tumor sites and suppressed M2-type signaling pathways, such as ATF6-TGFBR1-SMAD3, as well as chemokines including CCL17, CCL22, and CCL24." (PMID 39033109, 2024). "A statistically significant positive correlation was revealed between FoxP3 and CCL22 in S/M, but not between FoxP3 and CCL22 expressed by tumor cells." (PMID 39232378, 2024). "Tumor cells respond to immune cell attacks by expressing IDO1 and recruiting CCL22-positive cells." (PMID 39639005, 2024). "In lymphoma, CXCR4 recruits Tregs to the tumor mass, possibly through CCL17 and CCL22." (PMID 39000453, 2024). "CD8+ T cell secret higher levels of CCL22 and interferon‐γ (IFN‐γ) to increase PD‐L1 and IDO in Tregs which result in the accumulation of Tregs in cancer cells, and create a favorable environment for tumor growth eventually." (PMID 38349050, 2024). "Specifically, SOX12 transactivated CCL22, which resulted in the accumulation and enhanced activity of CCR4+Tregs within the tumor, whereas SOX18 up‐regulated CXCL12 expression, attracting CXCR4+TAMs and CXCR4+Tregs into the tumor." (PMID 39072947, 2024). "DNMT3A was significantly enriched in the CCL22 and CCR4 promoter regions in tumor tissues." (PMID 39513112, 2024). "Another recent study showed that loading immunogenic peptides and CCL22 siRNA into exosomes could expand CD8 + T cells and repress regulatory T cells within tumor microenvironment upon intramuscular administration." (PMID 39054529, 2024). "Mature mDCs specifically expressed CCR7, CCL17 and CCL22 to recruit infiltrating T cells, which transduced immune signals and recruits peripheral T cells in TME with strong migration and regulatory capabilities, thus playing an anti-tumor role." (PMID 39256364, 2024). "RCC patients with an increased plasma CCL17/CCL22 ratio had decreased overall survival, and patients with increased expression of the receptor for these cytokines (CCR4) had worse overall survival in multiple tumor types, including RCC." (PMID 37568390, 2023). "ESCC TAM-released CCL22 promoted tumor invasion and reduced patient survival via activation of the CCR4/DGKα/FAK complex in ESCC cells, revealing opportunities for targeting the tumor-promoting microenvironment to achieve anticancer effects." (PMID 37198402, 2023). "In the tumor microenvironment, CCL22 induces Treg infiltration, which further inhibits the function of CD8T cells and NK cells, forming an immunosuppressive environment and ultimately leading to tumor growth." (PMID 36969873, 2023). "As shown in tumor models, MDC/CCL22 is vital for recruitment of intratumoral T regulatory cells." (PMID 37685890, 2023). "Irradiated tumor tissues and cancer cells recruit chemokines such as CCL22 and CXCL12 and produce a range of cytokines such as TNF-α, TGF-β, IL-1, IL-6, and GM-CSF which could recruit tumor-infiltrating lymphocytes (TILs) into radiation site." (PMID 37259456, 2023). "Tumor cells and TAMs recruit CCR4+ Tregs to the TME via secretion of chemokine CCL22." (PMID 38264664, 2023). "In the context of MIP immunotherapy, our findings reveal type-1 IFN dependent CCL22 suppression and consequently reduced Treg migration as a so far unknown mechanism involved in MIP mediated anti-tumor activity." (PMID 37122749, 2023). "Therefore, mRNA expressions of chemokines CCL2, CCL17 and CCL22, as well as IL-6, IL-18, TNF-α and IFN-γ, in tumor tissues and H22 cells were detected by RT-qPCR." (PMID 36674931, 2023).
tumor (continued). "TAMs‐released CCL22 activates intratumoral CCR4/FAK/AKT axis, which induces the phosphorylation of Gli1 Ser112/Thr115/Ser116 sites, and stimulates Gli1 activity to induce the stemness and metastasis of tumor cells." (PMID 37846367, 2023). "The recombinant ligands CCL22 and CCL2 in this study were used in concentrations of 50 ng/mL, and it is not clear from our data what concentration will be required in vivo to efficiently reroute immune cells towards tumor sites." (PMID 36834542, 2023). "M2 TAMs promote tumorigenesis, stemness maintenance, HGOS metastatization and immunosuppression on the activity of tumor-infiltrating lymphocytes (TILs) by releasing immunosuppressive soluble factors as IL-10, TGF-β2 (transforming growth factor-β2) and CCL22 (chemokine (C-C motif) ligand 22)." (PMID 36614241, 2023). "Interestingly, high levels of MCP-1 correlate with a higher percentage of Th2 cells compared to Th1 in primary tumor tissue and induce macrophages to secrete Th2, which recruits the chemokines CCL17 and CCL22." (PMID 36286034, 2022). "Indeed, TAMs in the patch stage produce proinflammatory chemokines (e.g., CXCL5, CXCL10), whereas in the tumor stage they produce Th2 chemokines (e.g., CCL17, CCL22)." (PMID 35409404, 2022). "Our in vitro coculture system experiments and xenograft animal model revealed that TAM-derived CCL22 directly induced ESCC cell invasion and lymphatic metastasis by inducing EMT and promoting MMP secretion from tumor cells, expanding the tumor-promoting effect of CCL22 on ESCC." (PMID 35962191, 2022). "Importantly, CCR4 and its ligands CCL17 and CCL22 produced by TLS mature DCs, macrophages or tumor cells were shown to be involved in the Treg recruitment to the inflamed sites." (PMID 36566320, 2022). "Notably, the pathomechanism of metastatic breast cancer involves primary tumor growth in mammary pads, which activates the expression of CCL17 and CCL22 in the lungs." (PMID 36555280, 2022). "M2 phenotypic markers, such as CCL22, HIF-1a, Ym1, and MMP-9, which are involved in immunosuppression, angiogenesis, epithelial–mesenchymal transition, and invasion, were significantly upregulated by tumor challenge compared to the WT group." (PMID 35216272, 2022). "We grouped these samples by tumor type and examined FOXP3, CCL17, and CCL22 expression levels." (PMID 35025968, 2022). "The expression of Il4, Il13, Ccl11, Ccl17 and Ccl22 mRNA was increased two- to fourfold, whereas the expression of Tslp mRNA was not changed, in the skin lesions of Ddx5∆KC mice compared with Ddx5fl/fl mice at day 16 post-MC903 administration." (PMID 36271146, 2022). "Besides, the expression of IL-6 and TNF-α were upregulated while the expression of IL-10, CCL22, Arg-1 and CD206 were downregulated in the tumor tissues from ACEA-treated group." (PMID 35641479, 2022). "Therefore, like CCL22, CRR7 plays a crucial role in the migration of tumor cells to the lymphatic system and makes a crucial contribution to the metastasis and expansion of TSCC." (PMID 35480305, 2022). "In both cases, tumor-produced chemokines CCL17 and CCL22 trigger Treg migration by activating the CCR4 chemokine receptor, and, in both cases, the viral protein LMP1 may be central to this process." (PMID 35025968, 2022). "Chemokines, the ligands of chemokine receptors, are a family of interactive chemotactic cytokines, used to coordinate cell migration and home in the body CCL22 is the ligand of CCR4 transmembrane protein, which is mostly produced by tumor cells and tumor-infiltrating macrophages." (PMID 35176085, 2022). "We found that CCL17 and CCL22 production in different EBV+ tumor cell lines mirrored the levels of production of the EBV protein LMP1, and that the LMP1 gene on its own was sufficient to trigger chemokine expression and Treg migration into a mouse tumor model." (PMID 35025968, 2022).
tumor (continued). "Although no direct evidence has been found yet in tumors, CD26-mediated cleavage of CCL22 could affect its primary function as CCR4+ Treg recruiter and as such contribute to a tumor unfriendly environment." (PMID 34503058, 2021). "It was reported that CD163+ tumor-associated macrophages could inhibit T-cell proliferation and activation by secreting CCL22, IL-10, and TGF-β and recruiting regulatory T cells (Tregs) to tumor tissues." (PMID 35155189, 2021). "Given that CCL22 acted as an essential attractive signal of Tregs recruitment in various cancers, and that Foxp3 was the highly specific marker of Tregs, higher CCL22 and Foxp3 levels in HBV+ tumor implied higher intratumoral Tregs infiltration than HBV‐ tumors." (PMID 31769216, 2020). "Tumor evoked B regulatory cells (tBregs) play a primary role in lung metastases by the conversion of resting anti-tumor CD4+ T cells into FoxP3+ expressing Treg cells through the paracrine action of TGFβ and CCL22 expressed from lung." (PMID 33414786, 2020). "This precise mechanism may also explain why Treg cells are recruited into NSCLC tumor tissues, as TGF-β and CCL22 are also enriched in these areas." (PMID 32425930, 2020). "Most of the tumor-infiltrating CD4+ cells in gastric MALT lymphoma were shown to be FOXP3+ Tregs, and these Tregs were recruited by tumor cells through the chemokines CCL17 and CCL22, secreted by FOXP3+ Tregs." (PMID 30999581, 2019). "By contrast, expression of CCL22 was not upregulated in tumor tissues compared to healthy breast tissue and showed no impact on Treg infiltration." (PMID 30572845, 2018). "CCL1, but surprisingly not CCL22, showed a significant correlation with the number of tumor-infiltrating FoxP3+ Treg (p< 0.001)." (PMID 30572845, 2018). "Several chemokine-chemokine receptor pairs have been proposed to be responsible for recruiting Tregs to tumors including chemokine receptors CCR4, CCR10, CCR8 or CXCR3 expressed on infiltrating Tregs, responding to CCL22, CCL28, CCL1 or CXCL9-11 in the tumor microenvironment, respectively." (PMID 28290464, 2017). "The results indicated that Ccl17 (but not Ccl22) expression was significantly upregulated 10 wks following tumor cell inoculation." (PMID 28415693, 2017). "Furthermore, fucoidan inhibited tumor cells migration and CD4+ T lymphocytes, especially Treg cells, recruitment induced by M2 macrophages conditioned medium through suppression of CCL22." (PMID 27775051, 2016). "However, the CKM cocktail tended to inhibit expression of CCL22, CXXL12, as well as FoxP3 in our in vivo tumor model." (PMID 26956047, 2016). "No statistically significant main effects of tumor or interactions with time were evident for other inflammation-related genes (Il-6, Ccl5, Ccl1, Ccl22, Cx3cl1; p>0.05)." (PMID 27548621, 2016). "Regarding the mechanisms involved in the increased recruitment of macrophages into ARF−/− tumor xenografts, upregulation of chemokines and growth factors including CCL-17, CCL-22, CCL-5 and TGF-β might be critical." (PMID 27572316, 2016). "Gene expression analysis in pretumor mammary glands showed that all growth factors and chemokines observed to be elevated before tumor development in continuous HFD mice at 13 weeks of age (i.e., Tgfa, Ccl1, Ccl17, Ccl20, Ccl22, and Tgfb1) were elevated in LFD-HFD mammary glands at this time." (PMID 26526858, 2015). "NF-κB may promote the tumor formation and progression through up-regulation of its downstream effectors including TGF-β, IL-10, CCL2, COX-2, VEGF and CCL22." (PMID 26683520, 2015). "Furthermore, IL-17A produced by MDSCs recruits Treg cells at tumor sites via up-regulation of chemokines CCL17 and CCL22 and enhances their suppressor function via up-regulation of CD39 and CD73." (PMID 23372655, 2013).
tumor (continued). "Using mouse models, several approaches, including the use of specific antibodies, antagonists, or siRNA, have been used to block the CCL22/CCL17 – CCR4 axis, resulting in reduction in Treg frequencies and a concomitant increase in anti-tumor activity (40, –42)." (PMID 23874342, 2013). "Ligands for CD194 (e.g., CCL17 or CCL22) were in contrast to IL-6 and TGF-β not highly expressed in the tumor tissue, altogether indicating a conversion from CD8+ rather than a tumor-directed migration as the cause for the observed infiltration." (PMID 22110523, 2011). "In ELISA test for CCL19 and CCL22 of various CIK groups, it was founded that k-ras-DCs can apparently enhance CIKs' migration activity and can improve their migration capacity towards tumor cells." (PMID 22347323, 2011). "Concurrently, a cluster of chemokines (e.g., chemokine ligand 22 [CCL22]; and C‐X‐C motif chemokine ligand 12 [CXCL12]) are secreted to promote recruitment and infiltration of immunosuppressive cell populations, creating a permissive environment for tumor proliferation and metastatic dissemination." (PMID 41427020, 2025). "Previous findings of the present authors showed that CCL22 and CCR4 mRNA levels were higher in CC tissues compared with para-carcinoma tissue and normal cervix, and overexpression of CCL22 and CCR4 mRNA attributed immune disequilibrium in tumor microenvironment and promoted carcinogenesis." (PMID 39513112, 2024). "By analyzing the effect of MAP2K3 expression levels on chemokines in the tumor immune microenvironment, the results showed elevated expression of several chemokines in the MAP2K3 high expression group; such as CXCL10, CCR5, CCR10, CCL5, CCL7, CCR2, and CCL22 (upper part)." (PMID 38938778, 2024). "For instance, TAM derived cytokines, such as IL‐6, IL‐1β, IL‐8, TNF‐α, CCL‐17, and CCL‐22 significantly contribute to proliferation of GC cells, immunosuppression and angiogenesis in TME through the mediation of immune surveillance which support tumor growth and metastasis as a result." (PMID 38349050, 2024). "For instance, tumor/adjacent confined suppressive dendritic cells (i.e., DC subcluster 5) have been identified as a subset of dendritic cells (c21) with high expression of CD274, LAMP3, and CCL22, which may negatively regulate immune cells." (PMID 36333338, 2022). "Mechanisms that mediate this reduced recruitment of Tregs to HNSCC tumor microenvironments following BRB-E administration are still under active investigation, although chemokine-dependent infiltration via Ccl1, Ccl18, and Ccl22, and Vegfa-dependent recruitment are potential mechanisms." (PMID 36016924, 2022). "Hence, we suggested that the up-regulated expression of CCL22 and CD206 in CCL5−/− mice after cryo–thermal therapy could play a positive role in anti-tumor activity of macrophages." (PMID 35327361, 2022). "Interestingly, we observed that the IL2RAhi-CCL22+-Treg cells could recruit and enrich themselves through secreting the CCL22-CCR1 combination in all tumor samples." (PMID 35907904, 2022). "We found that CCL22 increased the phosphorylation of various intratumoral signaling substrates, especially FAK, the crucial hub that transduces tumor microenvironmental signals into tumor cells and regulates multiple malignant phenotypes during tumor progression." (PMID 35962191, 2022). "Ddx5 was increased in the whole skin lesions of MC903- or IMQ-treated Cd93–/– mice compared with their wild-type counterparts, along with fewer plaques on the ears or dorsal skin and reduced expression of Il4, Il13, Ccl11, Ccl17 and Ccl22 or Cxcl1, Cxcl2, Ccl20, Il23, Il17a and Il36γ." (PMID 36271146, 2022). "Interestingly, tumor secretion of CCL22 was found to be positively correlated with intratumor Treg infiltration and with aggressive tumor features such as high histological grade, lack of ER and PgR expression, and HER2 amplification." (PMID 34944971, 2021).
tumor (continued). "Moreover, M2 macrophage also releases cytokines and chemokines, such as IL-6, TNFα, and CCL22, activates TGF-β signaling pathway, and promotes angiogenesis and epithelial–mesenchymal transition, thereby facilitating tumor progression." (PMID 35047494, 2021). "Although evidence that CD26 downregulation preserved the intact CCL22 isoform was not provided, preservation of intact CCL22 in this setting could contribute to CCR4+ SS tumor cell accumulation in the skin." (PMID 34503058, 2021). "Importantly, HBV infection was associated with higher levels of CCL22 and Foxp3 than no HBV infection, indicating more Tregs (Foxp3 positive) were recruited into the tumor tissues of HBV carriers than noncarriers." (PMID 31769216, 2020). "Also, in tumor tissues, HBV infection appeared to cause more dramatical changes in gene expression of p65, miR‐23a and CCL22 than no infection." (PMID 31769216, 2020). "Thus, naturally occurring Foxp3+ T-regs may be induced to migrate from the peripheral blood to the tumor sites by the chemokines CCL17, CCL22, and CCL5 and then increase in number by tumor-related factors to create a favorable environment for tumor growth." (PMID 29772686, 2018). "Thus, elimination of Treg cells within the tumor microenvironment, for example by local micro-injection of anti-TGF-β or anti-CCL22 monoclonal antibodies might be an effective therapeutic approach against SSCC." (PMID 26020249, 2015). "Analyses of purified tumor-infiltrating CD45+ cells indicated that Lov treatment increased mRNA levels for M1 markers, which was statistically significant for IFNγ and IL-1β, whereas it downregulated M2-like markers (with significant differences for IL-10, CD206 and CCL22)." (PMID 24317954, 2013). "Although CCL22 was not analyzed in these studies, the potential effect of Ahr on CCL22 transcription is likely to be contextual and therefore, dependent on multiple factors from the tumor microenvironment." (PMID 23720663, 2013). "Taken together, these data suggest that the chemokine balance in tumors of HiAnx mice is shifted towards CCL22, which attracts regulatory/suppressor T cells that suppress anti-tumor immunity, and away from CTACK, which may attract protective anti-tumor T cells." (PMID 22558071, 2012). "Importantly, though, with our PCLS and in situ data, we cannot distinguish whether the ZEB1-dependent CTL abundance (in situ) and the CCR2/CCR4-dependent tumor control (PCLS) are regulated by a direct recruitment of CD8 + T cells by CCL2 and/or CCL22 or other alternative mechanisms." (PMID 40595293, 2025). "Although the interaction between CCL22 and its receptor CCR4 may recruit regulatory T cells (Tregs) into the TME, thereby bolstering tumor immune evasion, it also fosters the infiltration of anticancer tumor-infiltrating lymphocytes (TILs), presenting a dual effect." (PMID 39512767, 2024). "Thus, it is not clear whether the high levels of CCL22 originate from the tumor or are produced systemically." (PMID 28481241, 2017). "The enhanced recruitment by CCL22 produced by EBVaGC cells, the decreased emigration due to CCR7 downregulation on the Treg surface, the higher proliferation rate, and the lower apoptosis rate of Tregs at tumour sites may promote the accumulation of Tregs in EBVaGC." (PMID 26673957, 2015). "Other CC chemokines including CCL3, CCL4, CCL5 (RANTES), and CCL22 (macrophage-derived chemokine) and some CXC chemokines, in particular CXCL8, may also be involved in TAM recruitment, because they are highly expressed in many human tumors and various tumor cell lines." (PMID 25125485, 2014). "Therefore, we speculated Foxp3 +Tregs aggregate surrounding the tumor of BC were not merely dependent on CCL22 but via other chemotaxis." (PMID 24124553, 2013). "The association between the COX2 and MDSCs/Treg attractants CXCL8 and CCL22, and suppressive factors IDO1 and IL-10 were observed exclusively after the BCG treatment of human BlCa tumor tissues, but not at baseline." (PMID 33809455, 2021).